ADGRA2 (adhesion G protein-coupled receptor A2)
Description:
Endothelial receptor which functions together with RECK to enable brain endothelial cells to selectively respond to Wnt7 signals (WNT7A or WNT7B). Plays a key role in Wnt7-specific responses, such as endothelial cell sprouting and migration in the forebrain and neural tube, and establishment of the blood-brain barrier (By similarity). Acts as a Wnt7-specific coactivator of canonical Wnt signaling: required to deliver RECK-bound Wnt7 to frizzled by assembling a higher-order RECK-ADGRA2-Fzd-LRP5-LRP6 complex. ADGRA2-tethering function does not rely on its G protein-coupled receptor (GPCR) structure but instead on its combined capacity to interact with RECK extracellularly and recruit the Dishevelled scaffolding protein intracellularly. Binds to the glycosaminoglycans heparin, heparin sulfate, chondroitin sulfate and dermatan sulfate.
Synonyms: GPR124; KIAA1531; TEM5; DKFZp434C211; DKFZp434J0911; FLJ14390
Tractability: Antibody: UniProt places it where antibodies can reach, with high confidence; its Gene Ontology location is reachable by antibodies, with high confidence; UniProt predicts a signal peptide or a membrane-spanning region; the Human Protein Atlas places it where antibodies can reach.
Target class: Family B G protein-coupled receptor; Membrane receptor
Gene: Protein-coding gene on chromosome 8 (37,784,191 to 37,844,896, forward strand). Ensembl gene ENSG00000020181.
Subcellular location: Cell membrane; Cell projection, filopodium
Subcellular location (Human Protein Atlas): Plasma membrane; Vesicles
Gene Ontology:
Molecular function: protein binding; G protein-coupled receptor activity; transmembrane signaling receptor activity
Biological process: canonical Wnt signaling pathway; cell surface receptor signaling pathway; central nervous system development; endothelial cell migration; G protein-coupled receptor signaling pathway; positive regulation of canonical Wnt signaling pathway; regulation of angiogenesis; regulation of chemotaxis; regulation of establishment of blood-brain barrier; sprouting angiogenesis
Cellular component: plasma membrane; Wnt signalosome; membrane; cell surface; filopodium
Genetic constraint (gnomAD): Loss-of-function variants: 59 observed, 77.69 expected, observed/expected ratio (o/e) 0.76, 90% interval 0.62 to 0.94. The synonymous counts are far from expectation, so gnomAD's model fits this gene poorly and the ratio says little. Missense variants: 1,650 observed, 1,591.1 expected, observed/expected ratio (o/e) 1.04, 90% interval 1 to 1.08. Synonymous variants: 823 observed, 703 expected, observed/expected ratio (o/e) 1.17, 90% interval 1.11 to 1.24.
Homologues: Orthologues: chimpanzee ADGRA2 (99% identical), dog ADGRA2 (91% identical), pig ADGRA2 (91% identical), mouse Adgra2 (88% identical), rat Adgra2 (88% identical), rabbit ADGRA2 (87% identical), guinea pig ADGRA2 (84% identical), macaque ADGRA2 (83% identical), tropical clawed frog adgra2 (57% identical), zebrafish adgra2 (51% identical). Paralogues in human: ADGRA3 (42% identical), ADGRA1 (17% identical), ADGRB1 (14% identical), ADGRL1 (14% identical), ADGRL2 (14% identical), ADGRB2 (13% identical), ADGRL3 (13% identical), ADGRB3 (12% identical), ADGRG4 (12% identical), ADGRG6 (12% identical), ADGRF5 (12% identical), ADGRE5 (11% identical), and 30 more.
Diseases named in the same sentence as ADGRA2 in open-access papers:
ADGRA2 is named in the same sentence as 46 diseases in open-access papers, as found by Europe PMC text mining. Sharing a sentence is not in itself a finding about the gene and the disease. The quoted sentences say what the papers report.
glioblastoma (4 papers, 2015 to 2023). The most malignant astrocytic tumor (WHO grade IV). "In glioblastoma the alteration of ADGRA2 expression reduced cell proliferation." (PMID 36230614, 2022). "Furthermore, the altered expression of ADGRA2 in glioblastoma significantly decreased the proliferation of the cancer cells by disrupting the mitotic progression and chromosome segregation, while TEM5 also plays a role in VEGF-induced tumor angiogenesis." (PMID 36230614, 2022).
breast carcinoma (3 papers, 2015 to 2023). "HER2-zero breast cancer was found to have gains in 08q24.21 (MYC) and 08p11.23 (FGFR1, ADGRA2, ZNF703)." (PMID 37264417, 2023). "Most proteins are moderately to highly expressed in several breast cancer cases with at least one antibody checked, the exception being ADGRA2, ADRB3 and STAR, whose genes are also not over-expressed at the mRNA level." (PMID 32987805, 2020).
colorectal cancer (3 papers, 2022 to 2025). A primary or metastatic malignant neoplasm that affects the colon or rectum. "GPR124/ADGRA2 is a member of the ADGRA group of aGPCRs and was identified originally due to its significant expression in the colorectal cancer vasculature; hence, it was alternatively named the tumor endothelial marker 5 (TEM5)." (PMID 39859266, 2025).
pancreatic cancer (2 papers, 2022). "In pancreatic cancer it has been shown that patients with alterations in ADGRA2 had a worse overall survival." (PMID 36230614, 2022).
B-cell lymphoma (1 paper, 2022). "Canine primary B-cell lymphoma samples showed underexpression of ADGRA2 compared to non-neoplastic controls." (PMID 36230614, 2022).
bone neoplasm (1 paper, 2024). A benign, intermediate, or malignant neoplasm involving the bone or articular cartilage. "In osteosarcoma, combination of β-elemene and paclitaxel inhibited bone neoplasm growth via downregulating ADGRA2, suggesting a potential role for ADGRA2 in therapy response." (PMID 38217005, 2024).
colorectal tumors (1 paper, 2024). "ADGRA2 was originally identified in the endothelial cells that form the neovasculature in invasive colorectal tumors." (PMID 38217005, 2024).
encephalitis (1 paper, 2023). An acute inflammatory process affecting the brain parenchyma. "To see if ADGRA2 appeared in hit lists of viruses not strongly associated with encephalitis, we examined the norovirus protease cleavage sites." (PMID 36851756, 2023).
hypospadias (1 paper, 2023). Hypospadias is the displacement of the urethral meatus on the ventrum of the penis. "While these non-synonymous homozygous ADGRA2, EGF, F13A1, IRF6, and GSTP1 genes mutation might encode mutant proteins, they do not provide a prediction of the phenotype, but may contribute to more accurate assessments of the orofacial clefts or hypospadias." (PMID 37238140, 2023).
lymphoma (1 paper, 2022). A malignant (clonal) proliferation of B- lymphocytes or T- lymphocytes which involves the lymph nodes, bone marrow and/or extranodal sites. "Indeed, high expression of ADGRA2 and its role in lymphoma is unknown." (PMID 36230614, 2022).
tumor (20 papers, 2005 to 2025). "To validate the role of ADGRA2 and ADRB3 expression in chemotherapy response and prognosis, we used a NACBC validation set, which consisted of 156 pre-treatment tumor samples of BC patients who received NAC with follow-up information available." (PMID 38217005, 2024).
cancer (7 papers, 2016 to 2025). A tumor composed of atypical neoplastic, often pleomorphic cells that invade other tissues. "Aberrant expression of ADGRA2 has also been found in other types of cancers." (PMID 38217005, 2024). "Next, we addressed the function of lncMB2 and lncMB1. lncMB2 is a predominantly nuclear transcript, whose proximal genes ZNF703 and ADGRA2, mapping about 360 Kb and 460 Kb apart from lncMB2 locus (AC091182.1), respectively, are both related to cancer." (PMID 34359754, 2021).
infection (1 paper, 2023). The state of being infected such as from the introduction of a foreign agent such as serum, vaccine, antigenic substance or organism. "ADGRA2 was found in all nine neuroinvasive viruses, suggesting a possible role in infection." (PMID 36851756, 2023).
ADGRA2 also shares sentences with these, for which no sentence is quoted: Stroke (6 papers); atherosclerosis (5); lung carcinoma (3); non-small cell lung carcinoma (3); central nervous system diseases (2); Infertility (2); intracerebral hemorrhage (2); lung adenocarcinoma (2); melanoma (2); brain arteriovenous malformation (1); brain diseases (1); brain tumors (1); Cerebral ischemia (1); cleft lip (1); coronary artery disease (1); depression (1); diabetic nephropathy (1); dilated cardiomyopathy (1); frontoparietal polymicrogyria (1); gastric cancer (1); Hyperglycemia (1); Hypertension (1); ischemia (1); ischemic stroke (1); kidney diseases (1); metastatic tumors (1); Miscarriage (1); Obesity (1); orofacial cleft (1); osteosarcoma (1).
A further 3 diseases each share a sentence with ADGRA2 in 1 paper.